TAFA3 (TAFA chemokine like family member 3)
Description:
Plays a role in the regulation of microglia polarization.
Synonyms: FAM19A3; TAFA-3
Tractability: Antibody: UniProt places it where antibodies can reach, with high confidence; UniProt predicts a signal peptide or a membrane-spanning region; its Gene Ontology location is reachable by antibodies, with medium confidence.
Gene: Protein-coding gene on chromosome 1 (112,718,905 to 112,727,235, forward strand). Ensembl gene ENSG00000184599.
Subcellular location: Secreted
Gene Ontology:
Molecular function: receptor ligand activity
Biological process: negative regulation of microglial cell activation; positive regulation of microglial cell activation; signal transduction
Cellular component: extracellular region
Genetic constraint (gnomAD): Loss-of-function variants: 17 observed, 20.47 expected, observed/expected ratio (o/e) 0.83, 90% interval 0.57 to 1.25. The upper end of that interval is the gene's LOEUF score, 1.25, which puts it in group 5 of 6, group 1 being the genes least tolerant of losing a copy. Missense variants: 174 observed, 179.85 expected, observed/expected ratio (o/e) 0.97, 90% interval 0.85 to 1.1. Synonymous variants: 74 observed, 76.34 expected, observed/expected ratio (o/e) 0.97, 90% interval 0.8 to 1.18.
Homologues: Orthologues: macaque TAFA3 (98% identical), guinea pig TAFA3 (90% identical), rabbit TAFA3 (89% identical), pig TAFA3 (89% identical), rat Tafa3 (87% identical), mouse Tafa3 (86% identical), chimpanzee TAFA3 (74% identical), dog TAFA3 (68% identical), zebrafish tafa3b (68% identical), tropical clawed frog tafa3 (67% identical), zebrafish tafa3a (65% identical), zebrafish tafa4b (64% identical). Paralogues in human: TAFA2 (62% identical), TAFA4 (62% identical), TAFA1 (56% identical).
Diseases named in the same sentence as TAFA3 in open-access papers:
TAFA3 is named in the same sentence as 4 diseases in open-access papers, as found by Europe PMC text mining. Sharing a sentence is not in itself a finding about the gene and the disease.
TAFA3 shares sentences with these, for which no sentence is quoted: cancer (1 paper); Hypertension (1); Stroke (1); tumor (1).